CD4 (CD4 molecule)
Diseases named in the same sentence as CD4 in open-access papers (continued):
Sharing a sentence is not in itself a finding about the gene and the disease.
tumor (continued). "Although following CAR modification, cytotoxic CD8+ T-cells mediate the direct eradication of tumor cells, also CD4+ T helper cells (Th cells) have been identified as highly efficient and clinically important T-cells." (PMID 34926461, 2021). "In our study, the tumour microenvironment contained very few CD4+TILs (77.8%) because there were high numbers of TAMs that inhibit T-cell recruitment." (PMID 35201470, 2021). "Tumor-infiltrating lymphocytes are polymorphic, mainly existing in the microenvironment of tumor tissues; they include CD4+, CD8+ T cells, B cells, and NK cells." (PMID 33854546, 2021). "An immune-mediated response has also been proposed to cause tumor regression and is supported by in vivo and in vitro models reflecting the antitumor and tumor clearance response from CD4+ and CD8+ cells." (PMID 34372502, 2021). "We found upregulation of Granzyme B, MIP1α, and CD137 (4-1BB) in tumor-infiltrating CD4+ T cells, indicating activation and effector functions." (PMID 34975924, 2021). "In vitro, DCs loaded with these ExVs stimulated CD4+T cell proliferation, while in vivo immunization with them inhibited tumor growth in a mouse model whose splenocytes expressed high levels of type I cytokines." (PMID 33435564, 2021). "CD4+ helper T (Th) cells play a critical role in shaping anti-tumor immunity by virtue of their ability to differentiate into multiple lineages in response to environmental cues." (PMID 34012510, 2021). "The in vivo experiments confirmed that the targeted silence of CRNDE-h in CD4+ T cells attenuated the CRC tumor growth in mice." (PMID 33495437, 2021). "The CD4+ T cells subset can target malignant tumor cells using different approaches, either by directly killing tumor cells or indirectly modulating tumor microenvironments (TME)." (PMID 33809974, 2021). "In 2019, two separate preclinical studies independently highlighted the role of CD4+ T cells in enhancing the anti-tumour CD8+ T-cell response." (PMID 32457487, 2021). "Recently, the presence of tumor-specific CD4 T cells, specifically at the tumor site, was shown to be necessary for immune-mediated tumor rejection." (PMID 33332284, 2021). "Subjects treated with pHIFU + ICI had increased levels of CD8+IFNγ+ T cells, increased ratios of CD8+IFNγ+ to CD3+CD4+FoxP3+ and CD11b+Ly6G+ cells, and decreased CD11chigh cells in their tumours compared with controls." (PMID 34229458, 2021). "Here we established an enhanced, yet simple, method for identifying simultaneously CD8+ and CD4+ tumor-specific reactive TILs in vitro, using a combination of widely known and available flow cytometry assays." (PMID 34707600, 2021). "DC inducible effect on CD4+ T cell differentiation is suppressed by Tregs, depletion of which will drive anti-tumor potential conventional CD4+ T cells." (PMID 35145911, 2021). "CD4 CTLs are a CD4 subset with cytotoxic activity and can directly kill tumor cells by secreting granzyme B and perforin, while Th2 and Th17 cells inhibit cell-mediated immunity and promote tumor progression." (PMID 34209797, 2021). "Further, there was a significant increase in the percentage of tumor infiltrating CD4 and CD8 T cells." (PMID 34445092, 2021). "In our previous study, we also found that the tumor-specific immune response was mainly induced by CD4+ T cells after cryo-thermal therapy in a B16F10 model." (PMID 34576115, 2021). "Intracranial injection of CD4+ CAR-T in an NSG model of GBM showed durable anti-tumor efficacy and prolonged survival, while mice receiving CD8+ CAR-T cells recurred following an initial response." (PMID 34012451, 2021).
tumor (continued). "Considering the multidimensional role of CD4+ TH cells, it is of utmost importance to understand the biology of these cells and how they contribute to tumor immune responses." (PMID 34012451, 2021). "Of note, the lymphocytes are localized within the tumor core as well as in the invasive front, as indicated by CD4 positive lymphocytes in the corpus callosum, where GFP positive cells migrate to the contralateral hemisphere." (PMID 33435218, 2021). "Recent studies have found that CD4+ T lymphocytes play an integral role in the induction of tumor cell regression by immunotherapy." (PMID 34327142, 2021). "In brief, CXCL12 secreted in the TME recruits CD4+CD25+ Treg cells to the tumor sites to contribute to the growth and prosperity of HCC." (PMID 34386499, 2021). "GO terms in the gene signature for inflamed (tumor, CD4) were enriched for neutrophil migration, neutrophil chemotaxis and regulation of dendritic spine." (PMID 33791196, 2021). "Neutrophils from autologous tumor tissues and non‐tumor tissues were purified and co‐cultured with autologous blood CD4+ T cells." (PMID 34185422, 2021). "The result that emerged, embedding CD4+ cells in the 3D healthy and tumor matrices, was that the phenotypic heterogeneity found and maintained in the 2D cultures was lost in both experimental conditions." (PMID 34070750, 2021). "This vaccine platform was shown to elicit both CD8 and CD4 antigen-specific T cell responses in preclinical tumor models, leading to immunological memory and high vaccine efficacy." (PMID 34276686, 2021). "In adaptive immune response, including humoral response, soluble tumor antigen is recognized by specific B cells, matures, and produces tumor antigen-specific antibody with the help of CD4+ T cells." (PMID 33959032, 2021). "In particular, there is a growing body of literature showing the increased expression of TOX in CTCL both by tumor cells and by CD4+ and CD8+ reactive T-cells in skin and blood samples." (PMID 34685762, 2021). "Several of the upregulated genes are shared across all the tumor-predominant CD4 Clusters; however, each cluster also had unique expression markers." (PMID 33504936, 2021). "Anti-tumor immune cells including CD4+ Th1 cells (p = 0.009), NK cells (p = 0.033), M1 macrophage cells (p = 0.007), and plasmacytoid dendritic cells (PDC) (p = 0.010) had higher proportions in the CSMD1-mut group." (PMID 34828321, 2021). "Most studies believed that high tumor CD4+ T cells infiltration usually indicates a favourable prognosis." (PMID 33676448, 2021). "Multiplex immunofluorescence showed increasing tumor infiltration of CD4+ and CD8+ T cells in post-treatment samples among four patients." (PMID 34885150, 2021). "DUSP12 expression was positively correlated with the abundance of tumor-infiltrating CD4+ T cells, macrophages, neutrophils, dendritic cells, and expression of the immune-checkpoint moieties HARVC2, TIGIT, CTLA4 and PDCD1." (PMID 34414037, 2021). "In this study, we also found that our ncRNA signature was correlated with HCC tumor infiltration by B cells, M0 macrophages, Tregs, resting mast cells, monocytes and resting CD4+ memory T cells." (PMID 34093785, 2021). "CD4+ regulatory T (Treg) cells, dependent upon the transcription factor Foxp3, contribute to tumour immunosuppression but are also required for immune homeostasis." (PMID 33838058, 2021). "Following tumor rechallenge to these animals, active CD4 + T-cells in blood were significantly higher." (PMID 33649388, 2021). "Taken together, EZH2 inactivation enhanced the recruitment of T cells into the tumor region by upregulating chemokine expression and promoted naïve CD4+ T cells to differentiate into effector Th cells in the short term." (PMID 34737746, 2021). "Such factors include high tumor antigen load, dendritic cells, CD4+T cell infiltration, CD8+T cell infiltration, and pro-inflammatory cytokines, among others." (PMID 33345281, 2021).
tumor (continued). "Taken together, our data suggest that the CD4 + T-cell infiltrate and tumor gene expression are independently predictive of outcome in FL, and future research should consider functional studies to elucidate their mutual influence." (PMID 34267181, 2021). "They protect tumor cells from lymphocytes by inhibiting the T-cell-mediated cytotoxicity of CD4+ and CD8+ cells in malignancies such as multiple myeloma and breast cancer metastases." (PMID 34257573, 2021). "One mechanism of both primary and secondary resistance is the presence of CD4+Foxp3+ regulatory T cells (Tregs) in the tumor microenvironment." (PMID 34676831, 2021). "Tregs have an inhibitory effect on TILs which comprise of NK cells, cytotoxic CD8+ T cells, and CD4+ helper T cells, while TILs usually act as an important player in the defense against tumor growth." (PMID 33628741, 2021). "CCL5, a tumor-derived chemokine has been detailed to actively attract CD4+, CD8+, as well as NK cells, with monocytes and macrophages known to extensively colonize solid tumors and potentially promote angiogenesis." (PMID 34835785, 2021). "Some Chinese medicine compounds are capable of exerting anti-tumor effects through facilitating CD4+T lymphocytes differentiate to Th1 and attenuating Th2 response." (PMID 34722304, 2021). "Further immune cell infiltration analysis revealed that CD4+ T cells were the major infiltrated cells in the tumor microenvironment of GC." (PMID 34966745, 2021). "Improved tumor growth control in mouse tumor models was associated with higher frequency of CD8 and CD4 T cells, improved effector functions, re-polarization of CD4 toward Th1, and modulation of the tumor microenvironment (TME)." (PMID 34276686, 2021). "Adoptive transfer of neoepitope-specific CD4+ TH1 cells led to tumor regression in a patient with metastatic cholangiocarcinoma." (PMID 35097027, 2021). "We found that 30–40% of tumor-infiltrating CD4 T cells were Treg cells expressing the canonical lineage-specific transcription factor FoxP3 across tested tumor models, suggesting that a high frequency of Treg cells is a general characteristic of CNS tumors." (PMID 33976133, 2021). "In the presence of inflammation, citrullinated epitopes can be presented by MHCII molecules on tumours for recognition by CD4 T cells." (PMID 34858415, 2021). "The anti-tumor immune effect of CD8+ T cells can be enhanced by the action of CD4+ T cells, while Treg cells inhibit CD8+ T-cell proliferation." (PMID 34180352, 2021). "The microenvironment of tumor lesions is a complex system comprising immune cells such as B cell, CD4+ T cell, CD8+ T cell, macrophage and components of fibroblasts, endothelial cells across stages." (PMID 34453042, 2021). "LAG-3:MHC class II binding contributes to tumor escape from apoptosis and facilitates recruitment of tumor-specific CD4 T cells, but with a reduction of the CD8 T cell response." (PMID 34067904, 2021). "Both pharmacological inhibition and gene knockout of EZH2 in these models led to Treg recruitment of CD8+ and CD4+ effector T-cells, resulting in increased anti-tumour activity." (PMID 34439236, 2021). "Across all TMA spots, 126,653 cells were identified, including 2957 PD-1+ CD4+ T cells, 6161 Tregs, and 19,847 tumor cells." (PMID 34795254, 2021). "In both FAP and CRC patients, increased numbers of CD4+Foxp3+ Tregs have been shown in tumor-draining lymph nodes and tumor sites; the function of Treg cells remains controversial in both FAP and CRC." (PMID 33628741, 2021). "It has been documented that CD4+ cells are more plastic and play dual roles, namely antitumor or pro-tumor." (PMID 34616914, 2021). "These CD4+ICOShiIFN-γ-producing cells were able to recognize tumor antigens and their expansion increased the ratio of Teff/Treg cells in peripheral blood and tumors." (PMID 33777008, 2021).
tumor (continued). "The Hsp70-activated CD8+ and CD4+ T-Lymphocytes kill evasive tumor cells via the FasL–Fas interaction by inducing in them alternative cytotoxic processes, apoptosis and necroptosis." (PMID 34206968, 2021). "Although our signature was identified in CD4+ T cells, we took an agnostic approach to the relative contribution of T cell subsets to tumor immunity." (PMID 34534438, 2021). "The balance between tumor-infiltrating immune effector cells in the TME (such as CD4+ T cells and CD8+ T cells (or cytotoxic T lymphocytes, CTLs)) regulates the immune response to cytotoxic effects on tumor cells." (PMID 34298668, 2021). "Treg, the immunosuppressive subset of CD4+ T cells, physiologically regulates immune tolerance, but also plays a major role in tumor development." (PMID 33562138, 2021). "Concurrently, the adoptive transfer of neoantigen-specific CD4+ T cells achieved tumor regression in a metastatic epithelial cancer." (PMID 34513673, 2021). "On the other hand, in an intraocular lymphoma model, IL-17 expression in infiltrating CD4 T cells inversely correlated with tumor burden." (PMID 33859643, 2021). "Controlling tumor-infiltrating CD4+CD25+Foxp3+ Tregs has been considered an essential step for enhancing anticancer immune reactions." (PMID 34064074, 2021). "We also found that PRMT5 deficiency in tumor cells enhanced the secretion of the cytokines IFN-γ and TNF-α by CD4+ T cells, and the expression pattern of above checkpoints on CD4+ T cells was similar to that on CD8+ T cells." (PMID 34522232, 2021). "Because CD4+ T cells are activated through MHC class II molecules, DCs from a third party that share MHC class II molecules with a tumor-bearing host should also be available to generate the intended AAA-CD4+ T cells." (PMID 34625113, 2021). "Major histocompatibility complex (MHC) class II and its lymphocyte binding partner CD4 were both also overexpressed in tumor compared to normal brain tissue." (PMID 33431066, 2021). "Here, we investigate the interaction among neutrophils, CD4+ T cells, and tumor cells in tumor tissues, and find that, in GC, neutrophils can be recruited to GC tumors via CXCL6/CXCL8‐CXCR1‐mediated chemotaxis." (PMID 34185422, 2021). "Unexpectedly, treatment with urelumab* alone in both models resulted in fewer tumor CD8+ T cells while increasing the number of CD4+ T cells and myeloid cells." (PMID 34290245, 2021). "We demonstrate priming of tumor-specific CD4+ and CD8+ cells, including memory cells; the adaptive arm targets metastatic disease and induces immune memory." (PMID 34575893, 2021). "CD4+ T cells can target tumor cells in a variety of ways, either by eliminating tumor cells directly through cytolytic mechanisms or indirectly by regulating TME." (PMID 34456923, 2021). "Analysis of T cell numbers within the tumor showed a significant increase in the number of human CD4+ and a trend towards increased CD8+ T cell numbers in tumors treated with NC410 compared to control." (PMID 34121658, 2021). "Treg CD4+ cells which are very important in controlling tumor growth and response to immunotherapies are poorly represented." (PMID 33406104, 2021). "Collectively, these recent preclinical studies demonstrate the critical and versatile role of polyfunctional tumour-infiltrating CD4+ T cells in the overall anti-tumour immune response." (PMID 32457487, 2021). "TIL-Bs in HNSCC have the potential to contribute to antitumor immunity in a number of ways including presenting tumor antigen to CD4+ T cells." (PMID 34099645, 2021). "In general, we discovered that most tumor infiltrating immune cells localized in the central region of the tumor, including CD4+ GzmB+ T cells." (PMID 34631551, 2021). "Six immune cell types that frequently infiltrate tumors were selected, including CD4 + T cells, CD8 + T cells, regulatory T cells (Tregs), tumor-associated macrophages (TAMs), myeloid-derived suppressor cells (MDSCs) and neutrophils." (PMID 34675316, 2021).
tumor (continued). "Our recent work builds upon the work of Klug and colleagues, confirming that LDRT polarizes pro-tumor M2-macrophages to the antitumor M1-phenotype, enhances the infiltration of CD4+ T cells and NK cells, and downregulates TGF-β inhibitory cytokine." (PMID 34975924, 2021). "We found that most CD4+ T cells in tumor epithelium and tumor stroma had either a Th2 or Treg phenotype, whereas only low numbers of Th1, Th17 and Tfh cells were observed." (PMID 34868011, 2021). "Peter Cohen and his group described tumor specific CD4+ and CD8+ T cells expansion from unfractionated PBMCs using an activator of innate immunity." (PMID 34012451, 2021). "The proportions of tumor-infiltrating CD4+ T cells were lower in the high-ATGPI group than in the low-ATGPI group." (PMID 34616731, 2021). "The frequency of CD4 T cells is much lower in comparison with CD8 ones; thus, research concerning tumor-specific CD4 T cells is more difficult." (PMID 34208339, 2021). "Tumor infiltrating T lymphocytes, especially CD4+ and CD8+T cells and their immunoregulatory cytokines play an adaptive immune role." (PMID 34777372, 2021). "IL-10 and TGFβ have the potentiality to convert CD4+T cells into Tregs that further would help tumor progression." (PMID 34485117, 2021). "Recent study has confirmed that M2 macrophages activated by CD4+T derived IL-4 are the main cell type in various tumor tissues including breast cancer and are involved in tumor progression." (PMID 34618681, 2021). "At the same time, there was also massive tumor immune cell infiltration, such as M2 macrophages, M0 macrophages, resting memory CD4 T cells, and gamma delta T cells, in patients with GBM and high expression of RIM-BP2." (PMID 34976783, 2021). "Tumor CD200 expression was correlated with significantly decreased tumor infiltration from CD4-positive and CD8-positive T cells and decreased production of IFNγ and TNFα." (PMID 33804482, 2021). "The infiltration of CD4+/CD8+ T cells and B cells was increased, and the number of CD4+ T cells was decreased, in tumor-bearing mice after treatment with 6-gingerol." (PMID 33959009, 2021). "Tamoxifen induced a shift of mouse myelin-specific CD4 + T cells from a TH1 phenotype targeted against tumor cells towards a TH2 phenotype, indicating its damaging effect on antitumor immunity." (PMID 33413549, 2021). "On that basis, the aim of this study was to investigate the gene expression profile of tumor-infiltrating CD4+ T cells and to predict their potential roles in modulating antitumor immune function." (PMID 33301062, 2021). "Overexpressed lncRNA NNT-AS1 decreases tumor CD4 lymphocyte infiltration by activating the TGF-β signaling pathway in HCC." (PMID 34638971, 2021). "They observed DCs maturation, tumor protection, and polarization of the CD4+ T cell population towards the Th17 population." (PMID 33623783, 2021). "One concern is the elimination of tumor-suppressive CD4+ T cells, as these cells are known for their roles in direct tumor suppression and T-cell memory formation." (PMID 34493727, 2021). "Tumor samples in the RS group shown more dendritic cells resting, T cells gamma delta and T cells CD4 naïve than the RR group." (PMID 34395274, 2021). "In the Th1 related gene set, only TNSF11 showed good correlation where its expression was down and the DNA methylation was higher in CD4+ T cells from tumor." (PMID 34012510, 2021). "The reduction of T regulatory cells is important for changing the tumor microenvironment and shifting the immune response from “cold” to “hot”, allowing these anti-tumor CD4+ and CD8+ T cells access to malignant cells." (PMID 34136405, 2021). "We compared the changes in tumor infiltration levels of CD4, CD8, or Foxp3‐positive T cells in tumor tissues before and after EGFR‐TKI treatment, in the patients who developed EGFR‐TKI resistance." (PMID 33305905, 2021).